MDM2 (MDM2 proto-oncogene)
Diseases named in the same sentence as MDM2 in open-access papers (continued):
Sharing a sentence is not in itself a finding about the gene and the disease.
Warthin tumor (1 paper, 2009). An adenoma characterized by an oncocytic, often papillary, epithelial component, dense lymphoid stroma, and cystic spaces. "• Mdm-2 could play a tumor-suppressor role that might be implicated with the benign behavior of Warthin's tumor." (PMID 19445705, 2009). "Mdm-2 played a tumor-suppressor role that might be implicated with the benign behavior of Warthin's tumor." (PMID 19445705, 2009). "Twenty paraffin blocks of cases previously diagnosed as Warthin's tumor were collected for immunohistochemical staining with primary antibodies against mdm-2, p27Kip1 and bcl-2 using streptavidin-biotin immunoperoxidase staining system." (PMID 19445705, 2009). "The aim of the present study is to investigate the immunohistochemical expression of mdm-2, p27Kip1 and bcl-2 in Warthin's tumor of parotid gland and also to clarify the role of these proteins in the behavior of that tumor." (PMID 19445705, 2009). "This dual function of mdm2, suggested by other investigators, might explain the high level of expression of mdm2 in Warthin's tumor." (PMID 19445705, 2009).
α-synucleinopathy (1 paper, 2020).
tumor (2,000 papers, 1993 to 2026). "Remarkably, the results of the present study showed that the cytoplasmic PER2 localization was associated with increased MDM2 overexpression, further confirming MDM2 as a marker of tumor aggressiveness and drug resistance." (PMID 40521302, 2025). "Whilst GATA3 mutations are not yet targetable, synthetic lethal interactions between GATA3 and MDM2 in ER + BC supports pharmacological inhibition of MDM2, shown to significantly impair tumour growth in GATA3-deficient models." (PMID 41351070, 2025). "Among the PCNA-associated hubs, ATM, HDAC1, and MDM2 showed strong correlations with the infiltration of multiple immune cells, highlighting their roles in tumor–immune interactions." (PMID 40430573, 2025). "This promotes the transcriptional activation of anti-apoptotic genes (such as MDM2 and Bcl-2), contributing to T cell exhaustion, which is linked to diminished anti-tumor immunity." (PMID 40352941, 2025). "Similar to aSCLC, CCND1, CDK4, and MDM2 are among the most common amplifications associated with chromothripsis across tumor type." (PMID 39185963, 2025). ",37TP53 mutations, ATM loss, MDM2 amplification, and cyclin D1 amplification are also shown to occur more frequently in luminal B versus A tumours." (PMID 39921934, 2025). "Because of this, our goal was to investigate the possible role of this subunit in the pathogenesis of MM and determine its eventual association with MDM2 expression in tumor cells." (PMID 41303785, 2025). "It has been demonstrated how MDM2 inhibition can cause tumor suppression both in in vitro and in vivo models of various cancers." (PMID 40002221, 2025). "Here, NSD-Loss tumours are significantly more likely to undergo ecDNA amplification at the MDM2 locus than SD tumours (risk ratio = 5.83, FDR = 0.029)." (PMID 41509216, 2025). "In conclusion, we developed an innovative approach of targeting crucial genes associated with mitophagy in conjunction with MDM2 inhibitor treatment to effectively induce tumor cell death by enhancing pyroptosis." (PMID 39215364, 2024). "Combining these two approaches enhances tumor resistance to therapy, improves the anti-tumor efficacy of drugs, and does not appear to exacerbate the adverse reactions associated with MDM2 inhibitors." (PMID 39263534, 2024).
tumor (continued). "It is involved in cell growth and proliferation and has been implicated in tumor promotion by stabilizing MDM2 and influencing the progression of cell division." (PMID 39519555, 2024). "Gene MDM2 encodes a tumor suppressor whose deactivation can promote the development of malignancies in the retinal cells." (PMID 38540335, 2024). "As a tumor-associated antigen, MDM2 is overexpressed in most tumors, presents low expression in normal tissues, and is often associated with poor tumor prognosis." (PMID 39263534, 2024). "While both targeted and general defense mechanisms are activated by the Mdm2 inhibitor, it still increases the susceptibility of tumor cells to other drugs." (PMID 38540160, 2024). "Low mutation load of tumor and frequent chromosome structural anomaly, including amplification of the chromosome 12q13-15 region and the MDM2 gene, are DDLPS's defining property." (PMID 39606156, 2024). "Nine patients from the expansion cohort had paired tumor tissue biopsies performed, which revealed that downregulation of MDM2 expression mediated through ATRX was associated with clinical benefit." (PMID 37298520, 2023). "Several reports found that the MDM2/HIF1α and NF-κB pathways were implicated in the pathological process of inflammation as well as tumor." (PMID 36673369, 2023). "A germline single nucleotide polymorphism of the MDM2 promoter increased MDM2 expression, increased cancer risk, and accelerated tumor progression." (PMID 37821635, 2023). "Using the same method, T-cell clones with high affinity for other tumor-associated antigens, including MDM2, CEA, and gp100, have been isolated." (PMID 37649123, 2023).
tumor (continued). "In many human cancers, its tumor-suppressor function is impaired by loss-of-function mutations or due to overexpression of its main negative regulator (MDM2)." (PMID 37175549, 2023). "In vitro assays in a panel of LUAD cell lines showed that tumor cell response to MDM2-targeted therapy is associated with MDM2 amplification." (PMID 35158979, 2022). "Of interest, MDM2 is implicated in promotion of cell cycle progression and inhibition of apoptosis, as well as in the epigenetic silencing of tumor suppressor genes through RB/DNMT3A-dependent pathway." (PMID 36296971, 2022). "The quantity of 12q13-15 amplification and MDM2 upregulation appears to be associated with the degree of tumor dedifferentiation." (PMID 36439412, 2022). "As the result, SNP309T>G MDM2 is found to associate with accelerated tumor formation in a gender-specific and hormone-dependent manner." (PMID 35155432, 2022). "An Italian study tried to find genetic modifiers that accelerate tumor development in LFS families other than MDM2 promoter polymorphisms SNP309T>G (rs2279744) or shortness of telomere length by performing whole-exome analysis (WES) of the trio." (PMID 35246108, 2022). "Depletion and pharmacological inhibition of MDM2 significantly impaired tumor growth in GATA3-deficient models in vitro, in vivo and in patient-derived organoids/xenograft (PDOs/PDX) harboring GATA3 somatic mutations." (PMID 35440675, 2022). "MDM2 amplification was associated with poor clinical outcomes and significantly increased tumor growth rates with anti-PD-1/PD-L1 immunotherapy." (PMID 35785159, 2022). "To date, several tumor cell biomarkers, including MDM2/4, epidermal growth factor receptor mutation, DNMT3A, and FGF3/4/19, have been shown to be associated with HPD." (PMID 36428951, 2022).
tumor (continued). "Genetically, DDLPS is characterized by a low tumor mutational burden and frequent chromosomal structural abnormalities including amplification of the 12q13-15 chromosomal region and the MDM2 gene, which are defining features of DDLPS." (PMID 36439412, 2022). "In both HCC cells and tumor tissues, the mRNA level of MDM2 is significantly increased which is inversely associated with miR-145 expression." (PMID 34307654, 2021). "In line with this duality, Mdm2 is associated with a better or worse prognosis depending on the tumor type." (PMID 33806062, 2021). "In particular, since USP2 modulates the stability of critical tumor-associated proteins such as cyclin D1, Mdm2, and FASN, great efforts have been made to establish a USP2-targeting anticancer drug." (PMID 33530560, 2021). "The results of the analysis showed some significant associations between the MDM2 polymorphisms and tumor features." (PMID 33669778, 2021). "We performed a comparison of MDM2 expression in RCC tumor tissues versus normal tissues as well as a survival association analysis of RCC patients with MDM2 expression (high versus low)." (PMID 34384473, 2021). "Rb is often mutated and E2F1 activity increased in tumour cells, making these aspects relevant considerations for MDM2 inhibition therapy." (PMID 34911439, 2021). "Treatment with a MEK inhibitor resulted in decreased expression of p-ERK, causing significant anti-tumor synergy when combined with MDM2 antagonists." (PMID 32806555, 2020). "MDM2 amplification occurs in cancer and has been implicated in accelerated tumor growth, known as hyper-progression, following immune-checkpoint therapy." (PMID 32655895, 2020). "Targeting MDM2-loss in resistant tumor cell lines by siRNA or functional blockade by AMG-232 showed enhanced T-cell-mediated tumor killing versus control treatment regardless of PD-L1 expression changes." (PMID 32655895, 2020). "Ten translocations and one MDM2 amplification out of 12 structural variants (92% detection rate) were detected from the matched tumour samples." (PMID 33287361, 2020).